ZBTB18 (zinc finger and BTB domain containing 18)
Description:
Transcriptional repressor that plays a role in various developmental processes such as myogenesis and brain development. Plays a key role in myogenesis by directly repressing the expression of ID2 and ID3, 2 inhibitors of skeletal myogenesis. Also involved in controlling cell division of progenitor cells and regulating the survival of postmitotic cortical neurons. Specifically binds the consensus DNA sequence 5'-[AC]ACATCTG[GT][AC]-3' which contains the E box core, and acts by recruiting chromatin remodeling multiprotein complexes. May also play a role in the organization of chromosomes in the nucleus.
Synonyms: TAZ-1; RP58; ZNF238; C2H2-171; C1DELq42q44; C1DELq43q44; DEL1Q42Q44; DEL1Q43Q44; MRD22
Tractability: PROTAC: UniProt records ubiquitination sites on it; its protein half-life has been measured.
Gene: Protein-coding gene on chromosome 1 (244,048,547 to 244,057,476, forward strand). Ensembl gene ENSG00000179456.
Subcellular location: Nucleus
Subcellular location (Human Protein Atlas): Nuclear speckles; Nucleoplasm
Gene Ontology:
Molecular function: DNA-binding transcription repressor activity, RNA polymerase II-specific; protein binding; sequence-specific DNA binding; sequence-specific double-stranded DNA binding; DNA binding; DNA-binding transcription factor activity, RNA polymerase II-specific
Biological process: negative regulation of transcription by RNA polymerase II; positive regulation of transcription by RNA polymerase II; negative regulation of DNA-templated transcription; regulation of transcription by RNA polymerase II; skeletal muscle tissue development
Cellular component: heterochromatin; nuclear speck; nucleoplasm; nucleus
Genetic constraint (gnomAD): Loss-of-function variants: 1 observed, 36.94 expected, observed/expected ratio (o/e) 0.0271, 90% interval 0.009 to 0.13. The upper end of that interval is the gene's LOEUF score, 0.13, which puts it in group 1 of 6, group 1 being the genes least tolerant of losing a copy. Missense variants: 404 observed, 715.74 expected, observed/expected ratio (o/e) 0.56, 90% interval 0.52 to 0.61. Synonymous variants: 302 observed, 288.32 expected, observed/expected ratio (o/e) 1.05, 90% interval 0.95 to 1.15.
Gene-disease validity (ClinGen):
ClinGen rates the evidence that ZBTB18 causes each of these diseases.
complex neurodevelopmental disorder (autosomal dominant): Definitive. A disorder that involves more than one phenotype associated with the central nervous system, including but not limited to intellectual disability, autism, and seizures (epilepsy).
Homologues: Orthologues: chimpanzee ZBTB18 (99% identical), guinea pig ZBTB18 (99% identical), macaque ZBTB18 (99% identical), rabbit ZBTB18 (99% identical), mouse Zbtb18 (99% identical), rat Zbtb18 (99% identical), pig ZBTB18 (98% identical), dog ZBTB18 (97% identical), tropical clawed frog zbtb18 (87% identical), zebrafish zbtb18 (74% identical). Paralogues in human: ZBTB42 (40% identical), ZBTB1 (22% identical), HIC1 (20% identical), HIC2 (19% identical), ZBTB16 (18% identical), ZBTB7C (16% identical), PATZ1 (15% identical), PRDM1 (14% identical), ZBTB20 (14% identical), ZBTB45 (14% identical), PRDM14 (13% identical), ZNF410 (13% identical), and 24 more.
Diseases named in the same sentence as ZBTB18 in open-access papers:
ZBTB18 is named in the same sentence as 42 diseases in open-access papers, as found by Europe PMC text mining. Sharing a sentence is not in itself a finding about the gene and the disease. The quoted sentences say what the papers report.
microcephaly (11 papers, 2015 to 2024). A congenital or acquired developmental disorder in which the circumference of the head is smaller than normal for the person's age and sex. "Germline mutations in ZBTB18 in humans result in abnormal brain development, such as microcephaly and intellectual disability, and late-acquired somatic mutations can trigger certain brain-associated cancers." (PMID 38102126, 2023). "AKT3 (1q43-q44; MIM 611223) deletions lead to partially penetrant microcephaly although the contribution of ZBTB18 (1q44; MIM 608433) and HNRNPU (1q44; MIM 602869) mutation is possible." (PMID 32916978, 2020). "A nonsense mutation in ZBTB18 has been recently reported in a patient with ID, microcephaly, growth delay, seizures, and agenesis of the corpus callosum." (PMID 30819258, 2019). "Patients with pathogenic variants in ZBTB18 present with Intellectual Disability (ID) with frequent co‐occurrence of corpus callosum (CC) anomalies, hypotonia, microcephaly, growth problems and variable facial dysmorphologies." (PMID 29573576, 2018). "Zbtb18-deficient mice show features reminiscent of the 1q43q44 microdeletion syndrome including microcephaly and agenesis of the corpus callosum (AgCC)." (PMID 28283832, 2017). "The OFC is known for nine patients with ZBTB18 mutations [from the literature and our series] and three have microcephaly." (PMID 28283832, 2017). "A de novo deletion at 1q44q44 spanning HNRNPU and ZBTB18 has been described in cases with ID, EP, microcephaly, and hypogenesis of the corpus callosum." (PMID 30510536, 2018). "Our data confirm that AKT3 is the main gene driving microcephaly, ZBTB18 defect is responsible for AnCC and HNRNPU is the main gene accounting for epilepsy." (PMID 28283832, 2017). "The number of patients with microcephaly who had deletions including ZBTB18 (n = 21/22) and sparing ZBTB18 (5/27) was also significantly different (p = 4.25E−8)." (PMID 28283832, 2017). "A SOX2-bound neural enhancer within the Akt3 gene is connected to the Zbtb18 (ZFP238 in man) TF gene, whose mutation causes microcephaly in man and mouse; in man, deletions including AKT3, or translocations separating AKT3 from ZFP238 also cause microcephaly." (PMID 30849367, 2019). "ZBTB18 may also contribute to microcephaly and HNRNPU to thin corpus callosum, but with a lower penetrance." (PMID 28283832, 2017). "Four of the six deletions including coding sequences of AKT3 only and one of the two deletions encompassing ZBTB18 but not AKT3 were associated with microcephaly." (PMID 28283832, 2017). "The alignments of microdeletions found in patients with a known OFC and comparison of their gene content showed that microcephaly was present in all 20 patients with deletions encompassing both AKT3 and ZBTB18, regardless of the presence of HNRNPU in the deletions." (PMID 28283832, 2017).
Intellectual disability (9 papers, 2015 to 2025). "Zbtb18 is essential for cerebellum growth, patterning, and neuron development, and de novo variants in ZBTB18 are linked to intellectual disability." (PMID 38327830, 2024). "ZBTB18 encodes a transcriptional repressor shown to play a critical role in orchestrating brain development, and has been associated with non-syndromic intellectual disability." (PMID 36117209, 2023).
glioblastoma (7 papers, 2021 to 2025). The most malignant astrocytic tumor (WHO grade IV). "Moreover, an association has been reported between high levels of ZBTB18 promoter methylation and shorter progression-free survival of patients with glioblastomas." (PMID 33892786, 2021). "In these contexts, ZBTB18 expression regulates several pathways in glioblastoma, which are also active in ACP microenvironment and clearly related to tumor development." (PMID 40575267, 2025). "We further confirmed the binding of ZBTB18 to the promoters of a set of SREBP genes by qChIP analysis in glioblastoma cells." (PMID 36414381, 2023). "This study identifies a new mechanism of fatty acid synthesis regulation in glioblastoma that involves ZBTB18, CTBP, and LSD1." (PMID 36414381, 2023). "Our results outline a new epigenetic mechanism enrolled by ZBTB18 and its co-factors to regulate fatty acid synthesis that could be targeted to treat glioblastoma patients." (PMID 36414381, 2023). "ZBTB18 has been identified as a tumor suppressor in glioblastoma and colorectal cancer." (PMID 37297004, 2023). "With the goal to get a better insight into ZBTB18 transcriptional repressive mechanisms, we used mass spectrometry (MS) to identify ZBTB18 co-precipitated proteins in glioblastoma cells (SNB19), upon FLAG-ZBTB18 overexpression and subsequent anti-FLAG co-immunoprecipitation." (PMID 36414381, 2023). "The expression of ZBTB18 has been shown to be negatively regulated by methylation of the CpG island in its promoter region and to reduce proliferation as well as to promote apoptosis in brain tumors such as medulloblastoma (MB) and glioblastoma multiforme (GBM)." (PMID 33892786, 2021). "Because of the role of ZBTB18 as a negative regulator of the mesenchymal transformation in GBM, our results have important implications in cancer therapy as they might help to find more effective strategies to diagnose and treat glioblastoma." (PMID 36414381, 2023).
epilepsy (5 papers, 2017 to 2024). A brain disorder characterized by episodes of abnormally increased neuronal discharge resulting in transient episodes of sensory or motor neurological dysfunction, or psychic dysfunction. "Corpus callosum agenesis/hypoplasia and epilepsy aremostly associated with deletions of ZBTB18 and HNRNPUgenes in the patients with 1q43q44 deletion syndrome,respectively." (PMID 31210441, 2019). "The pro-epileptogenic effect of ZBTB18 alteration could be masked by the strong penetrance of HNRNPU-related epilepsy in patients with loss of both genes." (PMID 28283832, 2017). "Still, epilepsy is a feature of the ZBTB18‐related genetic disorder and a role for ZBTB18 haploinsufficiency in epileptogenesis can therefore not be definitely excluded based on our data." (PMID 29573576, 2018). "These CNVs contained or partially contained epilepsy-related genes, such as PRRT2 (16p11.2), ZBTB18 (1q43q44), and GABRB3 (15q11.2q13.1)." (PMID 39906551, 2024).
brain tumor (4 papers, 2021 to 2023). "Several negatively correlated genes, including FGF9, ARMCX1, PMP22, and ZBTB18 are involved in nervous system functions, such as glial cell growth, axon regeneration, myelin development and brain tumour suppression." (PMID 37077524, 2023).
glioma (3 papers, 2012 to 2024). A benign or malignant brain and spinal cord tumor that arises from glial cells (astrocytes, oligodendrocytes, ependymal cells). "It is worth mentioning that because ZBTB18 is almost uniformly low or absent in GBM cells, knockout studies should be performed using low-grade glioma cells, in which ZBTB18 is more expressed." (PMID 36414381, 2023). "Of note, patient-derived organoid models of lower grade gliomas have been recently established, which could represent a useful model for future investigation of the ZBTB18 function." (PMID 36414381, 2023). "Among the cytokines regulated by ZBTB18, CCL2 is known to be released by the glioma cells and to recruit myeloid-derived suppressor cells." (PMID 39516530, 2024). "We then analyzed ZBTB18 and IBA1 expression in a cohort of glioma samples belonging to different CNS WHO grades." (PMID 39516530, 2024). "Therefore, repressing SREBP-regulated genes could be an additional mechanism through which ZBTB18 counteracts mesenchymal transformation in non-mesenchymal gliomas, which others and we previously reported." (PMID 36414381, 2023).
hepatocellular carcinoma (3 papers, 2021). A malignant tumor that arises from hepatocytes. "ZBTB18 was reported to be upregulated by circTP63 and further promote hepatocellular carcinoma progression." (PMID 34195188, 2021). "In hepatocellular carcinoma (HCC), circTP63 is significantly upregulated in HCC tissues and cell lines, and circTP63 overexpression promotes tumor progression by sponging miR-155-5p and upregulating ZBTB18 expression." (PMID 34789260, 2021).
autosomal dominant mental retardation 22 (2 papers, 2019 to 2024). "Autosomal dominant non-syndromic intellectual disability 22 is a rare genetic disorder caused by the ZBTB18 gene." (PMID 38215144, 2024). "In addition to this variant, another de novo c.1307G>T (p.Arg436Leu) missense variant in ZBTB18 (MIM 608433; autosomal dominant mental retardation 22, phenotype MIM 612337) was found in this patient." (PMID 30819258, 2019).
colon cancer (2 papers, 2017 to 2021). "We next investigated the role of ZBTB18 on the migration and invasion capacity of colon cancer cells." (PMID 33892786, 2021). "Zinc finger proteins were significantly enriched in this list of 382 genes with expression/methylation associations, and we demonstrated the tumor suppressor activity of the zinc finger transcriptional repressor ZBTB18 in colon cancer cells." (PMID 33892786, 2021). "Among them DGK1, HTR7, FLRT3, and ZBTB18 co-occurred with established regulators of human colon cancer pathobiology." (PMID 29344557, 2017).
colorectal cancer (2 papers, 2021 to 2023). A primary or metastatic malignant neoplasm that affects the colon or rectum. "In good agreement, low expression of ZBTB18 mRNA was significantly associated with shorter survival in an independent cohort of 55 Stage III colorectal cancer patients from the TCGA cohort." (PMID 33892786, 2021). "To further investigate the impact of ZBTB18 silencing in colorectal tumorigenesis, we assessed the possible association between ZBTB18 expression and patient survival in a cohort of 132 cases with locally advanced (Dukes’ C) colorectal cancer." (PMID 33892786, 2021). "Importantly, an association was observed between low ZBTB18 expression in this cohort of 132 Dukes’ C colorectal cancer patients and shorter overall survival." (PMID 33892786, 2021). "Moreover, immunohistochemical analysis revealed that ZBTB18 is frequently lost or reduced in colorectal tumors, and reduced ZBTB18 expression was found to be associated with lymph node metastasis and shorter survival of patients with locally advanced colorectal cancer." (PMID 33892786, 2021). "Moreover, as a proof of concept, we demonstrate that the epigenetically silenced gene ZBTB18 has tumor suppressor activity and is a novel prognostic marker for patients with locally advanced colorectal cancer." (PMID 33892786, 2021). "As a proof of concept, we demonstrate that ZBTB18, a zinc finger transcriptional repressor that is frequently methylated in colorectal tumors, has tumor suppressor activity and is a novel prognostic factor in colorectal cancer." (PMID 33892786, 2021). "First, we showed that treatment of four colorectal cancer cell lines with low ZBTB18 expression and high promoter methylation with the demethylating agent decitabine (5-aza-2′-deoxycytidine) resulted in a significant increase of ZBTB18 mRNA expression." (PMID 33892786, 2021). "Therefore, strategies aimed at rescuing ZBTB18 expression or downregulating some of the downstream ZBTB18 targets genes may have therapeutic potential in colorectal cancer patients." (PMID 33892786, 2021). "Moreover, ZBTB18 protein levels assessed with the same antibody in a tissue microarray containing the 30 colorectal cancer cell lines used in this study significantly correlated with ZBTB18 mRNA expression, further confirming the specificity of the primary anti-ZBTB18 antibody used." (PMID 33892786, 2021). "As a proof of concept, we investigated the potential tumor suppressive function of the transcriptional repressor ZBTB18 (also known as ZNF238 or RP58), which belongs to the zinc finger C2H2 family, and whose role in colorectal cancer progression has not been previously addressed." (PMID 33892786, 2021).
developmental delay (2 papers, 2015 to 2017). "Except one, all patients with 1q43q44 microdeletions or point mutations in ZBTB18 and HNRNPU had developmental delay or ID with a wide range of severity." (PMID 28283832, 2017).
rhabdomyosarcoma (2 papers, 2012 to 2023). A rare aggressive malignant mesenchymal neoplasm arising from skeletal muscle. "NFIA is required for the proliferation of cervical cells, ZBTB18 for rhabdomyosarcoma, and TEAD3 for the urinary tract cells." (PMID 37297004, 2023).
Alzheimer disease (1 paper, 2025). A progressive, neurodegenerative disease characterized by loss of function and death of nerve cells in several areas of the brain leading to loss of cognitive function such as memory and language. "Our analysis identified several transcription factors with no previous association with Alzheimer's disease in astrocytes, including TOX3, MKX, ZBTB18, and ZNF382." (PMID 40656638, 2025).
colorectal tumors (1 paper, 2021). "Consistently, reduced ZBTB18 expression in locally advanced primary colorectal tumors was associated with shorter patient survival." (PMID 33892786, 2021). "Significant variability in ZBTB18 expression was observed in primary colorectal tumors, ranging from high levels comparable to the ZBTB18 expression found in normal colonic epithelial cells, to low or undetectable ZBTB18 expression." (PMID 33892786, 2021). "Reduced ZBTB18 expression in the primary tumors was associated with shorter patient survival and the average expression of ZBTB18 was further reduced in lymph node metastases compared to primary colorectal tumors." (PMID 33892786, 2021). "While high ZBTB18 expression was observed in normal colonic epithelial cells, a significant reduction of ZBTB18 immunostaining was frequently observed in primary colorectal tumors." (PMID 33892786, 2021). "Here, a validated anti-ZBTB18 antibody was used to assess the expression of this zinc finger protein in normal colonic samples as well as locally advanced primary colorectal tumors and lymph node metastases." (PMID 33892786, 2021). "Moreover, ZBTB18 protein expression was further reduced in lymph node metastases compared to primary colorectal tumors." (PMID 33892786, 2021).
Glucose intolerance (1 paper, 2024). Glucose intolerance (GI) can be defined as dysglycemia that comprises both prediabetes and diabetes. "Since hepatic Zbtb18 deletion predisposes HFD-fed mice to serious glucose intolerance and insulin resistance, it is easy to take it as an indication that Zbtb18 plays a predominant role in alleviating the HFD-induced dysfunctional glucose and insulin responses." (PMID 38263084, 2024). "Also, increased expression of FXR significantly alleviates glucose intolerance and insulin resistance in the liver caused by Zbtb18’s absence." (PMID 38263084, 2024). "Moreover, the hepatic Zbtb18 rescue improved the glucose intolerance and insulin resistance of Zbtb18LKO mice, also beneficially inducing enhanced phosphorylation of AKT and GSK-3β in Zbtb18-deficient liver." (PMID 38263084, 2024).
glucose metabolic disorders (1 paper, 2024). "To prove FXR’s critical role in mediating the Zbtb18-induced protective effects against lipid and glucose metabolic disorders, we employed FXR gain or loss cultured MPHs and HFD-fed mice combining them with hepatic Zbtb18 alterations." (PMID 38263084, 2024).
Hepatic steatosis (1 paper, 2024). Steatosis is a term used to denote lipid accumulation within hepatocytes. "Of note, Zbtb18 overexpression effectively alleviated HFD-induced hepatic steatosis, including the improvements in hepatocyte ballooning and lipid deposition." (PMID 38263084, 2024). "Altogether, these data indicated that targeting hepatic Zbtb18 represents an effective approach to hinder the progression of liver steatosis in db/db mice." (PMID 38263084, 2024). "Altogether, Zbtb18 transcriptionally activates the FXR-mediated FAO and CLTC expression, which inhibits NLRP3 inflammasome’s activity alleviating inflammatory stress and insulin resistance, representing an attractive remedy for hepatic steatosis and fibrosis." (PMID 38263084, 2024).
Hyperglycemia (1 paper, 2024). An increased concentration of glucose in the blood. "Conversely, hepatic Zbtb18 overexpression alleviated hepato-steatosis, insulin resistance, and hyperglycemia in mice fed on a high-fat diet (HFD) or in diabetic mice." (PMID 38263084, 2024).